RHOXF2B (Rhox homeobox family member 2B)
Description:
Transcription factor maybe involved in reproductive processes. Modulates expression of target genes encoding proteins involved in processes relevant to spermatogenesis.
Tractability: Antibody: the Human Protein Atlas places it where antibodies can reach.
Gene: Protein-coding gene on chromosome X (120,072,264 to 120,077,690, reverse strand). Ensembl gene ENSG00000203989.
Subcellular location: Nucleus
Subcellular location (Human Protein Atlas): Plasma membrane; Nucleoplasm
Gene Ontology:
Molecular function: DNA-binding transcription factor activity, RNA polymerase II-specific; RNA polymerase II transcription regulatory region sequence-specific DNA binding; DNA binding
Biological process: positive regulation of gene expression; neuron development; regulation of transcription by RNA polymerase II; regulation of DNA-templated transcription
Cellular component: chromatin; nucleus
Homologues: Orthologues: macaque RHOXF2 (78% identical). Paralogues in human: RHOXF2 (99% identical), ARX (19% identical), PAX7 (18% identical), RHOXF1 (18% identical), ESX1 (18% identical), PAX3 (17% identical), PRRX2 (17% identical), PITX1 (16% identical), UNCX (16% identical), PAX6 (16% identical), PRRX1 (16% identical), OTP (16% identical), and 38 more.
Diseases named in the same sentence as RHOXF2B in open-access papers:
RHOXF2B is named in the same sentence as 4 diseases in open-access papers, as found by Europe PMC text mining. Sharing a sentence is not in itself a finding about the gene and the disease. The quoted sentences say what the papers report.
Azoospermia (1 paper, 2014). Absence of any measurable level of sperm,whereby spermatozoa cannot be observed even after centrifugation of the semen pellet. "The four exons in each of RHOXF2 and RHOXF2B were sequenced in 47 patients with oligospermia or non-obstructive azoospermia." (PMID 25780578, 2014).
male infertility (1 paper, 2014). The inability of the male to effect fertilization of an ovum after a specified period of unprotected intercourse. "Mutations in the RHOXF2 and RHOXF2B genes (which encode homeodomain proteins exclusively expressed in the testis) might explain some cases of male infertility." (PMID 25780578, 2014).
RHOXF2B also shares sentences with these, for which no sentence is quoted: Infertility (1 paper); oligospermia (1).